TCF4 (transcription factor 4)
Diseases named in the same sentence as TCF4 in open-access papers (continued):
Sharing a sentence is not in itself a finding about the gene and the disease.
psychiatric disorder (26 papers, 2013 to 2026). A disorder characterized by behavioral and/or psychological abnormalities, often accompanied by physical symptoms. "Pathogenic variants in this gene have been linked to a rare genetic disorder, Pitt–Hopkins syndrome, and TCF4 polymorphic variants are associated with several socially significant diseases, including various psychiatric disorders." (PMID 39722673, 2024). "Accumulating evidence has suggested that miR-137 and its target genes, CACNA1C, and TCF4, are amongst the most robustly implicated genes in psychiatric disorders." (PMID 36193501, 2022). "In this review, we describe the known functions of TCF4 and the pathological consequences of TCF4 genetic variants linked to psychiatric disorders." (PMID 33414364, 2021). "Strong biomarker candidates such as brain-derived neurotrophic factor (BDNF) and transcription factor 4 (TCF4) gene variants are unsuitable due to their involvement in other major psychiatric disorders." (PMID 34829325, 2021). "Query of rs314267 revealed a two order of magnitude allelic difference in the motif match p-value for TCF4—a gene itself implicated in cross-psychiatric-disorder risk." (PMID 34294677, 2021). "The precise molecular mechanisms through which TCF4 mutations contribute to PTHS pathophysiology, as well as the role of TCF4 variants in other psychiatric disorders such as SCZ, remain to be further elucidated." (PMID 33414364, 2021). "To this end, we investigated transcription factor 4 (Tcf4) because of its persistent expression in the adult mammalian brain throughout the lifespan and noted association with both neurodevelopmental and psychiatric disorders." (PMID 34564703, 2021). "Common genetic variants in and around TCF4 are associated with a range of neurodevelopmental and psychiatric disorders." (PMID 32765228, 2020). "Genomic alterations that affect TCF4 function or levels increase the risk of neurodevelopmental or psychiatric disorders." (PMID 32765228, 2020). "In addition, we took the opportunity of interrogating two additional genes (CACNA1C and TCF4) widely implicated in major psychiatric disorders that were also included in the targeted panel." (PMID 35590255, 2022). "For CACNA1C and TCF4, two genes that have been repeatedly linked to major psychiatric disorders from GWAS and a few rare variant association studies, we studied the role of deep-sequenced rare variation across a spectrum of mental illnesses." (PMID 35590255, 2022). "Overall, our study not only uncovers the functional role of the psychiatric disease-risk gene Tcf4 in mature neurons but also provides critical insights into the structure-function regulation of adult neurons, revealing involvement of previously unappreciated molecular pathways." (PMID 34564703, 2021). "Notably, TCF4 has been repeatedly identified as a candidate risk gene for different psychiatric diseases and Tcf4tg mice display behavioral endophenotypes such as fear memory impairment and hyperactivity." (PMID 33519394, 2020). "We profiled Tcf4 gain and loss-of-function mutants in the context of G×E interactions with a comprehensive test battery assessing various behaviors’ and condensed these to behavioral “domains” and “superdomains” adapted from selected research domain criteria (RDoc) for psychiatric disease models." (PMID 33037178, 2020). "Although much is yet to be comprehended, the general role of TCF4 in psychiatric disease has clearly emerged, materializing TCF4 as a key regulator of neural function, including learning, memory, language, and sociability." (PMID 33414364, 2021). "Given the importance of Tcf4 in psychiatric diseases, we investigated its role in adult neurons using cell-specific deletion and genetic tracing in adult animals." (PMID 34564703, 2021). "In this study, we developed the PsyCoP workflow and applied it to the two-hit psychiatric disease mouse model of Tcf4 overexpression in combination with psychosocial stress in adolescence." (PMID 33519394, 2020).
psychiatric disorder (continued). "This study highlights the regulatory role of TCF4 in interneuron development and provides compelling evidence to support the biological rationale linking TCF4 to the developing cortical interneuron and psychiatric disorders." (PMID 35965434, 2022). "TBR1 has also been associated with ASD and TCF4 with BPD, and TOP3B was shown to bind multiple mRNAs derived from ASD-linked genes, raising the possibility that STX1A-mediated neurotransmitter release is dysregulated in multiple psychiatric disorders." (PMID 31142819, 2021). "These included the MHC region; DRD2, the dopamine D2 receptor involved in mood and emotion; MEF2C, a gene that regulates synaptic function; TCF4, a regulator of prefrontal neuronal excitability and RBFOX1, a gene splicing regulator that has also been implicated in other psychiatric disorders." (PMID 31576797, 2020). "Furthermore, supporting the primary role of miRNAs in psychiatric disorders, miRNA-137 (miR-137) maps to a risk locus in SCZ and regulates other risk genes, like CACNA1C (calcium channel, voltage-dependent, l-type, alpha-1C subunit) or TCF4 (transcription factor 4)." (PMID 32033412, 2020). "To understand the link between TCF4 and psychiatric disorders (PSD), we first conducted an integrative transcriptomics analysis on public bulk RNA-Seq and single-cell RNA-seq (scRNA-seq) data of the fetal brain to determine the spatiotemporal expression pattern of TCF4." (PMID 35965434, 2022).
neurological disorders (16 papers, 2013 to 2026). "Differentially expressed or spliced genes in the compound heterozygous mutant animals include ortholougus genes causing human neurological disorders such as Abca7, Zfp365, Kmt2c, Madd and Tcf4." (PMID 37294900, 2024). "Our findings greatly extend our knowledge of the spatiotemporal and cell type-specific expression patterns of TCF4 in the brain, and hence, lay the groundwork to better understand TCF4-linked neurological disorders." (PMID 32765228, 2020). "Understanding the roles of Da in adult brain possibly give insights about the roles of TCF4 in the adult brain that could be beneficial in understanding the mechanisms of the neurological diseases associated with TCF4." (PMID 41500834, 2026). "TCF4 has also been associated with the development of neurological disorders, including PTHS." (PMID 40149012, 2025). "To gain more insight into TF function in mature neuron, we focused on Tcf4, whose role in adult brain neurons remain unknown despite its association with multiple neurological diseases." (PMID 34564703, 2021). "The transcription factor TCF4 has been implicated in the genetic aetiology of several neuropsychiatric and neurological disorders, however, the identity of TCF4 target genes in neuronal cells remains largely unknown." (PMID 29228394, 2018). "Patient 1’s CSF also enriched TCF4 and KIF21A peptides relative to CSF samples from pediatric patients with other neurologic diseases." (PMID 34694339, 2021).
genetic disorder (10 papers, 2017 to 2026). "This work delineates pathological mechanisms in neural cells harboring TCF4 mutations and provides a potential target for therapeutic strategies for genetic disorders associated with this gene." (PMID 35501322, 2022). "PTHS is a genetic disorder mainly related to deletions or variants in the transcription factor 4 gene (TCF4; OMIM#602272) encoding a broadly expressed basic helix–loop–helix (bHLH) protein controlling the activity of many genes, most of which are involved in the nervous system development." (PMID 39655047, 2024). "Taken together, our data reveal novel cellular and molecular phenotypes in human cells with clinically relevant TCF4 mutations and show that these aberrations are reversible, providing routes for therapeutic intervention in individuals carrying genetic diseases associated with this gene." (PMID 35501322, 2022). "FECD is a complex and heterogenous genetic disease, where a trinucleotide CTG repeat expansion within the third intron of transcription factor 4 (TCF4) is found in approximately 75% of FECD patients." (PMID 38704483, 2024).
infection (9 papers, 2012 to 2025). The state of being infected such as from the introduction of a foreign agent such as serum, vaccine, antigenic substance or organism. "Infection of Calu-3 cells followed by qRT-PCR analyses revealed that SARS-CoV-2 induces expression of multiple Wnt target genes including TCF4, c-jun, and ATF3." (PMID 40295745, 2024). "To define the mechanism by which β-catenin transcription is inhibited by SARS-CoV-2, we evaluated the impact of infection on transcription factors known to interact with β-catenin: TCF1, TCF3, TCF4, and LEF1." (PMID 41156605, 2025). "During measurement of β-catenin/Tcf4-dependent TOP-flash reporter activity, CR infection induced a 2-fold increase in reporter activity at 48 h post-infection." (PMID 24278135, 2013). "Western blot analysis revealed a dose-dependent decrease in Tcf-4 or β-catenin protein expression in SW480 and HCT116 cells at 48 h post-infection with the respective adenoviral vectors." (PMID 23029137, 2012). "The results indicated that, with the replication of the MDV RB1B strain, the expression level of Wnt/β-catenin signaling pathway-related genes β-catenin, TCF4, LEF1, c-Myc, and Cyclin D1 were significantly downregulated after 24 h of RB1B strain infection and significantly upregulated at 60 h." (PMID 38638910, 2024). "However, in response to infection, male mice exhibited higher expression levels of CDKN1B, and CTNNB1 (KO, 1A3), TCF4 (1A0, 6A2), TAP1, and TAP2, (1A0), CDKN1A, (1A3, 6A2), MARCO, and MMP12 (1A3), CCND1, CDK2, IRF and MYC (6A2) compared to females." (PMID 32670284, 2020).
adenocarcinoma (7 papers, 2008 to 2024). A common cancer characterized by the presence of malignant glandular cells. "Thus, in the present study we evaluated each of 60 cases of sporadic adenocarcinoma, alongside adjoining and normal mucosa specimens of colorectum in humans, for mutation and expression analysis of the gene coding for TCF-4 protein." (PMID 32265994, 2020). "Recent in vivo experiments in a xenograft brain lung metastasis model postulated a functional role for lymphoid enhancer factor 1/T cell factor 4 (LEF1/TCF4) in a subgroup of adenocarcinomas." (PMID 23224985, 2013). "IHC revealed nuclear TCF4 in all adenocarcinoma samples, whereas only 36 % depicted nuclear LEF1 and nuclear β-catenin signals." (PMID 23224985, 2013). "First of all, our data strongly support a role of LEF1/TCF4 in at least one subgroup of cerebrally metastasized adenocarcinoma patients." (PMID 23224985, 2013). "Their role in humans is still unclear, thus we analyzed LEF1, TCF4, β-catenin, and early stage prognostic markers in 25 adenocarcinoma brain metastases using immunohistochemistry (IHC)." (PMID 23224985, 2013). "The similarly high levels of expression of TCF4 in the nucleus of the colorectal normal epithelia and adenocarcinomas are consistent with the results of previous studies by immunohistochemistry and in situ hybridization." (PMID 18992165, 2008). "We analyzed the nuclear expression of p-c-Jun, TCF4 and β-Catenin in relation to the pT and pN stages in adenocarcinomas." (PMID 18992165, 2008).
cardiovascular disease (4 papers, 2013 to 2026). "Our results reveal a key role for TCF4 in safeguarding EC identity and preventing EndoMT, suggesting a therapeutic potential of targeting TCF4 for EndoMT-related cardiovascular diseases." (PMID 41160897, 2025). "Six genes (TKT, TCF4, SWAP70, DDHD2, ARHGAP31, and LTB) showed significant associations of genetic variants with the risk of cardiovascular disease." (PMID 36204511, 2022).
brain disorder (3 papers, 2018 to 2021). A disease affecting the brain or part of the brain. "Collectively, these studies implicate TCF4 in a range of brain disorders that are commonly associated with cognitive dysfunction." (PMID 32765228, 2020). "Therefore, our studies revealed the importance of Tcf4 in controlling OPC survival during OB development, which provides novel insights into the mechanisms underlying TCF4-associated brain disorders." (PMID 33462220, 2021). "The increased OPCs in the OB could potentially impact neuronal functions, which provides insights into TCF4-related brain disorders." (PMID 33462220, 2021).
gastrointestinal tumor (1 paper, 2022). "Meanwhile, in the progression of gastrointestinal tumor, the synergy between NR5A21 and β-catenin/TCF4 signaling upregulate the expression of cyclin D1, cyclin E1, and c-Myc which is the downstream targets of the canonical Wnt signaling." (PMID 35633416, 2022).
metabolic disorders (1 paper, 2025). "TCF4 influences hepatic glucose metabolism, and circadian misalignment may exacerbate metabolic disorders." (PMID 40024983, 2025).
TCF4 also shares sentences with these, for which no sentence is quoted: Angelman syndrome (8 papers); endothelial corneal dystrophy (7); Fanconi anemia (4); Autoimmunity (3); Hypertension (3); Kleefstra syndrome (3); post-traumatic stress disorder (3); primary sclerosing cholangitis (3); T-cell acute lymphoblastic leukemia (3); amyotrophic lateral sclerosis (2); anaplastic astrocytoma (2); colorectal (2); Cornelia de Lange syndrome (2); COVID-19 (2); Down syndrome (2); Dravet syndrome (2); early infantile epileptic encephalopathy (2); Friedreich ataxia (2); frontotemporal dementia (2); head and neck squamous cell carcinoma (2); Insulin resistance (2); keratoconus (2); Mowat-Wilson syndrome (2); oral squamous cell carcinoma (2); pancreatic ductal adenocarcinoma (2); Timothy syndrome (2); adenomatous colon polyp (1); adenovirus infection (1); allergies (1); anemia (1).
A further 81 diseases each share a sentence with TCF4 in 1 paper.